PDK1 (pyruvate dehydrogenase kinase 1)
Diseases named in the same sentence as PDK1 in open-access papers (continued):
Sharing a sentence is not in itself a finding about the gene and the disease.
tumor (continued). "Since tissue hypoxia is a normal phenomenon in tumors, future studies should investigate whether PDK1 and HIF-1α form a positive feedback loop that regulates tumor progression." (PMID 38560503, 2024). "Additionally, knockdown of Serinc2 inhibited tumor growth and reduced the protein expression of c‐Myc, PFKP, LDHA, and PDK1 in vivo." (PMID 39417376, 2024). "Overall, this study showed the glut-3 and pdk-1 gene silencing as a suitable and effective radiosensitizing method to overcome resistance induced by the Warburg effect instauration in hypoxia condition, typical of some areas of GBM tumor." (PMID 38396757, 2024). "Previous studies have shown that HIF−1α directly induces the expression of many metabolic genes in cancer cells to enhance aerobic glycolysis, such as glucose transporters (GLUTs), pyruvate dehydrogenase kinase 1 (PDHK1), lactate dehydrogenase A (LDHA), to meet the energy needs of tumor growth." (PMID 38654163, 2024). "However, the MAPK4D254A mutant, which can promote PDK1 protein expression but cannot directly bind and activate AKT, exhibited limited tumor-promoting activity." (PMID 37531320, 2023). "Significant negative correlations were found of PDK1 expression with tumor diameter (p = 0.000) and higher overall survival (p = 0.010)." (PMID 37147361, 2023). "In contrast, knockdown of PDK1 leaves the MAPK4-AKT signaling axis largely intact in the MAPK4-overexpressing cells, which may account for the partially maintained tumor cell growth." (PMID 37531320, 2023). "Results revealed that there was no considerable variation in tumor mass between WT and PDK1-cKO mice (B P > 0.05)." (PMID 37828580, 2023). "Western blot results showed that S1PR1, cyclin B1, PDK1, and lamin B1 protein levels were significantly decreased, whereas P21, P62, histone H3, IGFBP7, and PAI-1 protein levels were significantly increased in S1PR1 knockout tumor tissue." (PMID 37828220, 2023). "Inhibitors of glycolysis-related genes, such as PDK1 and LDHA, located downstream of HIF-1α, could decelerate tumor growth." (PMID 37008055, 2023). "Collectively, these data suggest that MAPK4 promotes MNK1/2-mediated eIF4E S209 phosphorylation; however, unexpectedly, eIF4E S209 phosphorylation does not play a notable role in MAPK4 promotion of PDK1 protein expression or tumor growth." (PMID 37531320, 2023). "Furthermore, silencing PDK1 can reduce angiogenesis and increase tumor cell necrosis in OC316 and OVCAR3 tumor models." (PMID 38090580, 2023). "Besides its activity in phosphorylating/activating AKT in the phosphatidylinositol 3-kinase (PI3K) pathway, PDK1 also exhibits constitutive activity in phosphorylating many other AGC kinases, such as S6K, SGK, PKC, and RSK for tumor-promoting activities." (PMID 37531320, 2023). "The triple-drug combination significantly (p < 0.0001) reduced the gene expression levels of VEGF, VEGFR, PI3K, PDK1, AKT1, mTOR and GSK3β while it significantly (p < 0.0001) enhanced the expression of PTEN, when compared with the tumor-control (TC) and other treatment groups." (PMID 37025487, 2023). "Furthermore, a notable negative correlation emerges between the expression levels of PDK-1 and MAT2A and both tumor size and metastasis." (PMID 38063756, 2023). "Furthermore, the juxtaposition of therapies such as TRAIL and TMZ or PDK1 and CHK1 inhibitors reveals synergistic effects in the inhibition of tumor growth." (PMID 38002561, 2023). "Real-time qPCR analysis of glucose transporter and glycolytic genes in the xenograft tumor tissues showed that ACE2 overexpression suppressed the mRNA levels of SLC2A1, HK2, ENO1, PFKL, LDHA, and PDK1, while inhibition of Mas receptor with A779 restored the expression of glycolytic components." (PMID 37215979, 2023). "In this case, dual activation of AKT and PDK1 is necessary but not sufficient for the full tumor-promoting activity of MAPK4." (PMID 37531320, 2023). "HK2, PDK1, and LDHA are also reported to be key participants in the tumor glycolysis process." (PMID 37233956, 2023).
tumor (continued). "The formation of poorly differentiated BCs was convincingly observed in syngeneic mice tumor grafts with either PDK1- or PKCα-expressing cells, but not AKT1-expressing cells." (PMID 35159078, 2022). "Inhibiting PDK1 and PDK2 in such environments reduced the formation of tumor spheroids." (PMID 36474273, 2022). "Studies in tumor metabolism revealed that B7-H3 increases the expression levels of hypoxia-inducible factor 1 α (HIF1α), lactate dehydrogenase A (LDHA), and pyruvate dehydrogenase kinase 1 (PDK1), and therefore stimulates the Warburg effect by increasing glucose uptake and lactate production." (PMID 36159789, 2022). "Although PDK1 and PDK2 have similar biological functions in the chemoresistance and tumor progression of HNC, we found that only PDK2 was significantly elevated in the advanced stage of HNC and that PDK2 silencing predominantly inhibited the proliferation and colony formation abilities of HNC cells." (PMID 36474273, 2022). "The removed tumor tissues were subjected to Western blot, and it was confirmed that the protein expression of HIF-1α and its downstream glycolytic genes GLUT1, HK2 and PDK1 in the HNK treatment group was significantly lower than that in the control group." (PMID 35350760, 2022). "Furthermore, IHC assays indicated that PDK1, LDHA, and c-myc were upregulated in circPDK1-WT-overexpressing the subcutaneous tumor." (PMID 36068586, 2022). "To confirm these results, we knocked-down Pdk1 in APC; Sirt6IECΔ organoids and saw reduced organoid formation and growth, further supporting the involvement of glucose metabolism in Sirt6-driven tumor initiation." (PMID 35314684, 2022). "The HIF-1α could induce the activation of lactate dehydrogenase A (LDHA) and pyruvate dehydrogenase kinase 1 (PDK1) to catalyze the conversion of pyruvate to lactate, accordingly promote glycolysis to produce ATP in the anoxic tumor microenvironment." (PMID 35662730, 2022). "Furthermore, copper bounds PDK1, which then activated the downstream substrate AKT and led tumor development." (PMID 36276092, 2022). "Data here displayed places vitamin C as an unexpected capital inhibitor of tumor metabolism in KRAS mutant CRC, regulating the expression of PDK-1 and, therefore, the activity of the PDHC complex, boosting the conversion of pyruvate into Acetyl CoA within the mitochondria." (PMID 33664850, 2021). "The tumor-suppressive function of miR-335 is mediated by the suppression of COL11A1 expression, thereby reducing the invasive ability and chemoresistance of EOC cells via the Ets-1/MMP3 and Akt/c/EBPβ/PDK1 axes, respectively." (PMID 34944877, 2021). "PDK1 is a direct target of HIF-1α in cancer cells under both hypoxic and normoxic conditions, and its downregulation by short hairpin RNA reverts the glycolytic phenotype, inhibits tumor growth and reduces invasiveness in several tumor cell lines." (PMID 34439291, 2021). "Tumours demonstrate a growth advantage through a shift in metabolism, specifically, from oxidative phosphorylation to glycolytic metabolism, which is driven by HIF-1–pyruvate dehydrogenase kinase 1 (PDK1)." (PMID 34445354, 2021). "In current study, we show that the lack of TMEM116 stimulates TAp63 expression through PDK1 pathway and in turn inhibits cancer cell motility and tumor metastasis." (PMID 34789718, 2021). "Moreover, in human pancreatic cancer cells, OSU inhibits PDK1 and AKT phosphorylation, thereby decreasing tumor invasion." (PMID 34356673, 2021). "qRT-PCR detected the expression of SOX2-OT, miR-30d-5p and PDK1 in tumor cells of each group, indicating that overexpression of SOX2-OT could down-regulate miR-30d-5p and up-regulate PDK1 expression." (PMID 34394184, 2021). "PDK1 pathway is highly activated in NSCLC cells and a potential target for tumor therapy." (PMID 34868313, 2021). "In summary, unlike the roles of PDK1-3, the roles of PDK4 in tumor progression and the underlying molecular mechanisms remain largely unclear." (PMID 32489458, 2020).
tumor (continued). "However, in hypoxic tumor cells, HIF-1 target gene PDK1 is activated and PKD1 inactivates PDH, resulting in pyruvate being excluded from mitochondria." (PMID 33109235, 2020). "For instance, the PDK1 substrate serum/glucocorticoid regulated kinase family member 3 (SGK3) is frequently overexpressed in HCC and its downregulation reduced both colonies formation and tumour formation in nude mice." (PMID 31088502, 2019). "HOXA9 acts as a tumor suppressor and inhibits glycolysis in cSCC in vitro and in vivo by negatively regulating HIF-1α and its downstream glycolytic regulators, HK2, GLUT1 and PDK1." (PMID 29662084, 2018). "PDK1 mRNA and protein expression levels were significantly higher in tumor tissues compared with adjacent non-cancerous tissues." (PMID 29106390, 2018). "Then, we identified that miRNA-21 was directly transferred from tumor cells to HSCs in tumor parenchyma via exosomes, and miRNA-21 could convert HSCs to CAFs by down-regulating its target PTEN to activate PDK1/AKT signaling pathway." (PMID 30591064, 2018). "In summary, our results showed that tumor-derived exosomal miRNA-21 could convert HSCs to CAFs via down-regulating PTEN and activate PDK1/AKT signaling pathway to promote angiogenesis." (PMID 30591064, 2018). "Our results indicated that tumor-derived exosomal miRNA-21 could convert HSCs to CAFs by decreasing PTEN, leading to activated PDK1/AKT signaling pathway in HCC." (PMID 30591064, 2018). "Thus, these novel findings demonstrate that the glycolysis gatekeeper PDK1 has a critical role in BCSC reprogramming and provides a potential therapeutic strategy for breast malignancy." (PMID 29106390, 2018). "Moreover, H19 overexpression resulted in an increase of tumor sphere-formation capacity in MDA-MB-231 cells, whereas depletion of PDK1 limited this induction." (PMID 29106390, 2018). "Additionally, our results showed that the metastatic tumor cells in the cervical LNs positively expressed vimentin, ALDH1, and PDK1, suggesting they were endowed with EMT and CSC-like phenotypes." (PMID 27926487, 2017). "Furthermore, results showing a reduced tumor occurrence in PTEN+/−, PDK1 hypomorphic mice, compared to PTEN+/− mice, strongly support PDK1 as important therapeutic target in cancer driven by alterations of the PI3K pathway." (PMID 28287465, 2017). "Yet, this seems to not be the case in tumours resistant to PI3Kα inhibition, as recent research has shown that PDK1 is a new player actively underpinning this resistance." (PMID 29064423, 2017). "The present study investigated, by immunohistochemical analysis, the protein expression of HIF-1α, PDK1, PHD3, PFKFB4, and VEGFA, five genes extensively modulated in hypoxic conditions, the typical state of tumor microenvironment strictly connected with cancer cells growth and propagation." (PMID 29117193, 2017). "Moreover, the expression level of PDK-1 and MAT2A was found to be negatively correlated with the tumor size and metastasis." (PMID 28839175, 2017). "Previously, we showed that PDK1 plays an important role in regulating GBM metabolism via simultaneous targeting of mitochondrial epidermal growth factor receptor (mtEGFR) protein levels and signaling activities with resultant tumor regression." (PMID 28410193, 2017). "Interestingly, in addition to the effects on PDK1, Atglistatin treatment increased the expression of lipid transporter fatty acid binding protein 4 (FABP4) in tumor cells grown in transwell with adipocytes." (PMID 27588494, 2016). "In 2005 the Dent laboratory published studies which strongly argued that the PDK-1 inhibitor OSU-03012 (licensed by Arno Therapeutics from Ohio State University and called AR-12) was not primarily acting as a PDK-1 inhibitor to radio-sensitize tumor cells." (PMID 26887051, 2016). "Although originally thought to be an inhibitor of PDK-1, OSU-03012 (AR-12) was shown in 2005 not to primarily act as a PDK-1 inhibitor in its ability to radio-sensitize tumor cells." (PMID 27957385, 2016).
tumor (continued). "Local HT could contribute to changing tumor vessel perfusion and pO2, through activating HIF-1 and its downstream targets, such as VEGF and pyruvate dehydrogenase kinase 1(PDK1), and modifying tumor cell metabolism signaling pathways." (PMID 27384678, 2016). "In addition, PDK1 is an upstream kinase of AKT, which regulates activities of AKT, in turn, mediates the regulation of tumor cell growth, metastasis, and angiogenesis." (PMID 26684827, 2015). "Suppression of PDK1 to activate PDH flux also contributes to BRAF(V600E)-induced oncogene senescence, further suggesting that limiting glucose oxidation is important for tumor growth." (PMID 25621173, 2015). "To identify optimal therapeutic strategies, we first screened our tumor cell lines for growth inhibition and cell death after exposure to chemical inhibitors of MEK (PD0325901 and GSK1120212), PI3K (BEZ235 and GDC0941), PDK1 (OSU03012), and AKT (MK2206) at clinically achievable doses of ~ 0.1 μM." (PMID 26158412, 2015). "Furthermore, expression of PFKFB3, PFKFB4 and PDK1 was decreased by MTG16-expression; these genes are key regulators of glucose metabolism in tumor cells." (PMID 23840896, 2013). "The inability to achieve full tumor regression in this combination study may be a consequence of only blocking PI3K pathway signaling downstream through AKT, thus still allowing PDK1, PKC and Rac signaling to occur." (PMID 22935382, 2012). "However, Western blot analyses for two PDK isoenzymes, PDK-1 and PDK-2, showed less expression in c4 compared with WT tumours." (PMID 21612605, 2011). "The in vivo consequences of PDK1 transgene expression in the mammary gland, its effect on tumorigenesis, and its influence on the tumor promoting effects of PPARδ activation have not been investigated." (PMID 21297860, 2011). "In summary, PDK1 expression in the mammary gland was not oncogenic, but accelerated tumor formation in conjunction with a PPARδ agonist." (PMID 21297860, 2011). "Peroxisome proliferator-activated receptor β-mediated activation of ILK and PDK1 is controlled at the transcriptional level and is closely connected to the decrease of PTEN expression, commonly lost in tumours, including those of ovarian origin." (PMID 18349831, 2008). "Moreover, PDK1 inhibitor JX06 rendered cancer cells more sensitive to gefitinib treatment in vivo, and JX06 and gefitinib combination treatments have a synergic effect to inhibit tumor growth." (PMID 42004224, 2025). "Further mechanism studies showed that LRRC1 enhances PDK1 stability by promoting its deubiquitination via USP7, thereby increasing AKT1 phosphorylation levels and activating the AKT/GSK3β/β-catenin/VEGFA signaling pathway, ultimately accelerating tumor angiogenesis in HCC." (PMID 41369408, 2025). "The results showed that compared to the sh-NC group, the lactate and ATP contents in tumor tissues were significantly reduced in the sh-LHX9 group, and the mRNA and protein expression of glycolysis-related genes (GLUT1, HK2, LDHA, and PDK1) were also significantly reduced." (PMID 37980488, 2023). "Since our newly identified MAPK4-PDK1 axis can work with the MAPK4-AKT axis to promote cancer growth, we examined whether co-targeting PDK1 and AKT using PDK1 inhibitor GSK2334470 and AKT inhibitor MK2206 will be a valid approach to block MAPK4 tumor-promoting activities." (PMID 37531320, 2023). "Lastly, co-expression of MAPK4D254A and AKT1-DD only partially recapitulated the tumor-promoting activity of WT MAPK4 in the soft-agar assays, suggesting that MAPK4 activation of additional signaling cascade beyond PDK1 and AKT may be important to promote tumor cell anchorage-independent growth." (PMID 37531320, 2023). "Under the condition of accelerating the growth of tumor cells, the metabolic pathway changes from oxidative phosphorylation to the glycolytic pathway, which is mainly realized by upregulating the glycolysis-related proteins GLUT1, HK2, and PDK1 mediated by HIF-1α." (PMID 35350760, 2022).
tumor (continued). "PDK1 is a glycolysis-promoting enzyme that could reduce the conversion of pyruvate into acetyl-CoA and inhibit the mitochondrial oxidative phosphorylation (OXPHOS), thereby maintaining aerobic glycolysis in tumor cells." (PMID 36319992, 2022). "PDK1 and PDK2 silencing could reduce the tumor sphere formation of HNC cells." (PMID 36474273, 2022). "PDK1 overexpression partly reversed the biological function of miR-148a—including miR-148a’s ability to increase cell sensitivity to Adriamycin (ADR) treatment—inhibiting cell glycolysis, invasion and epithelial–mesenchymal transition (EMT), and inducing apoptosis and repressing tumor growth." (PMID 35892859, 2022). "Notably, at variance with the moderate antiproliferative effects observed in vitro, we found a dramatic negative impact of PDK1 silencing on tumor growth." (PMID 33562444, 2021). "Importantly, non-SPOP recognized PDK1 also promoted tumor growth in mouse, coupled with increased AKT kinase activity." (PMID 34353330, 2021). "Metabolic adaptation to hypoxia in tumours is primarily mediated by HIFs and includes the diversion of glucose-derived carbons from the TCA cycle and the conversion of pyruvate to lactate, and by upregulation of the enzymes pyruvate dehydrogenase kinase 1 (PDK1) and LDHA." (PMID 30886710, 2019). "Paradoxically, here we found that elevated CHCHD4 expression in tumour cells leads to significantly reduced levels of cellular lactate in normoxia and no significant change in PDK1 (data not shown), which is consistent with an increased respiratory drive in these cells." (PMID 30886710, 2019). "Although the tumor-suppressive role of AKT3-174aa prevents its druggable potential, we think that the low expression of AKT3-174aa may allow for AKT be easily exposed to p-PDK1 or SETDB1 in GBM, and this makes AKT more sensitive to activation cascades." (PMID 31470874, 2019). "PDK1 also inhibits TGF-β-mediated cell growth arrest and apoptosis by directly interacting with Smad proteins, revealing that PDK1 inhibition may be beneficial for tumor suppression." (PMID 29849900, 2018). "However, tumors in highly vascular regions such as tumor foci in the choroid exhibited no expression of PDK1." (PMID 28505181, 2017). "In this study, Eug could significantly decrease HER2, p85, PDK1 and AKT protein expressions in a dose-dependent manner in MCF-10AT cells or breast precancerous lesion model rats, which could further promote cell apoptosis and inhibit tumor progression." (PMID 28915591, 2017). "Enhanced expression of PDK1 in RNF126-depleted cells did not further suppress tumor growth." (PMID 27462466, 2016). "Moreover, inhibition of Akt phosphorylation, the primary target of PDK-1, is not consistently observed across all tumor cell lines even though apoptosis induction is comparable after celecoxib treatment." (PMID 23875171, 2013). "A noticeable finding was that expression of certain genes involved in tumor cell metabolism including 6-phosphofructo-2-kinase/fructose-2,6-biphosphatase 3 and 4 (PFKFB3 and PFKFB4), and pyruvate dehydrogenase kinase isoenzyme 1 (PDK1) was rapidly diminished when MTG16 was expressed." (PMID 23840896, 2013). "However, no changes were evident in other putative PDK1 downstream targets in either tumor histotype." (PMID 21297860, 2011). "In addition, the tumor promoting effects ofPPARδ in the mammary gland relate to activation of β-catenin/TCF signaling, which is increased in cellstransformed by PDK1." (PMID 18566686, 2008). "Moreover, we were concerned that PDK1-specific inhibitors would affect tumor cells at the time of intervention and that we could not properly evaluate the function of PDK1 in osteoclasts." (PMID 37828580, 2023). "However, the mechanisms of PDK1 in regulating tumor progression is not clear." (PMID 34221996, 2021).